GNAS (GNAS complex locus)
Diseases named in the same sentence as GNAS in open-access papers (continued):
Sharing a sentence is not in itself a finding about the gene and the disease.
Obesity (continued). "A pathogenic variant, NM_080425.3:c.2524C>T:p.Arg842Cys, was detected in GNAS in one patient with DOR and obesity." (PMID 39595984, 2024). "Many GOOS participants with GNAS variants showed impaired MC4R signalling, suggesting centrally MC4R-mediated hyperphagia leading to obesity." (PMID 39104441, 2024). "This prompted us to look for genetic variants in GNAS, PDE4D, and PRKAR1A, and for methylation alterations of GNAS locus in a cohort of Finnish patients who had developed severe obesity already in early childhood." (PMID 32318528, 2020). "Other studies have shown that genetic variations in several known imprinted genes, such as IGF2, INS and GNAS, have been associated with CMR traits, including adult obesity (BMI) and T2D." (PMID 26451733, 2015). "Further investigation is needed to clarify the exact role of GNAS in the development of obesity and hypertension and to identify possible target point for the reduction of the risk for metabolic diseases in later life of GDM fetuses." (PMID 25269528, 2014). "These regions were found near genes associated with obesity (MCR4), imprinting (GNAS), and glial cell formation (METRNL)." (PMID 22761590, 2012). "Previous studies in other mammalian species have shown that DNA sequence variation within the imprinted GNAS gene cluster contributes to several physiological and metabolic disorders, including obesity in humans and mice." (PMID 21214909, 2011). "Mutations associated with monogenic obesity follow autosomal recessive (LEP, LEPR, POMC, and PCSK1) or autosomal dominant (MC4R, SH2B1, SIM1, GNAS) modes of inheritance." (PMID 41751424, 2026). "Among other effects, GNAS variants may impair signaling of MC4R, a G‐protein–coupled receptor, leading to hyperphagia and early‐onset obesity." (PMID 40528426, 2025). "Children who inherit maternal, but not paternal, GNAS function‐altering variants frequently develop obesity." (PMID 40528426, 2025). "Recently, GNAS variants were described in 22 of 2548 patients with severe early-onset obesity (Genetics of Obesity Study [GOOS]), not previously noted to have PHP." (PMID 39104441, 2024). "As such, we speculate that the CC genotype of GNAS rs7121 regulates clopidogrel resistance, thereby affecting the responsiveness of related drugs via inflammation related to body obesity." (PMID 34609028, 2021). "Patients with maternally inherited GNAS coding exon mutations, but not those carrying mutations on the paternal allele, have obesity/overweight." (PMID 29280743, 2017). "In mice, disruption of the G protein α-subunit (one of the GNAS gene products) maternal (but not paternal) allele leads to severe obesity, hypertriglyceridemia, impaired glucose tolerance and insulin resistance." (PMID 28473845, 2017). "Absence of hormone resistance in patients with obesity does not exclude GNAS variants." (PMID 39104441, 2024). "Moreover, non-syndromic, monogenic obesity may result from such GNAS alterations." (PMID 39684386, 2024). "Several of the observed DMCs were located in genes related to T2D or obesity, such as ALOX12, PAMR1, and GNAS in WB; IRS1, LEP, and ADIPOQ in SAT; LCAT, FOXA2, KCNQ1, and GCKR in VAT; and PKD4, HNF4A, XBP1, and PON1 in LT." (PMID 29466957, 2018). "Furthermore, genetic variants thought to be implicated in BD such as BDNF, MTHFR, GNAS, and CACNA1C/D, have been hypothesized to overlap between BD and CVD, conferring risk of mood disorders in addition to risk of hypertension, type 2 diabetes, obesity, and dyslipidemia." (PMID 30761021, 2019). "Paternal GNAS mutations are associated with AHO, no hormonal resistance and no obesity, a constellation of features grouped under the term of pseudopseudohypoparathyroidism (PPHP) as well as with progressive osseous heteroplasia (POH)." (PMID 26583054, 2015).
Obesity (continued). "While obesity and short stature are long known features of PHP1A, it became only recently apparent that growth and metabolism are affected in both paternal and maternal epi/genetic alterations of the GNAS locus (for review:)." (PMID 25784961, 2015). "Whilst obesity and short stature are long known features of PHP1A, it became only recently apparent that growth and metabolism are affected in both paternal and maternal (epi)genetic alterations of the GNAS locus." (PMID 26583054, 2015). "Interestingly, the Arg842Cys variant was recently reported in a patient presenting with isolated obesity without the classical signs of pseudo hypoparathyroidism or Albright’s syndrome, related to GNAS alteration." (PMID 39595984, 2024). "Paternal GNAS mutations are associated with AHO, no hormonal resistance and no obesity." (PMID 25784961, 2015). "In addition, although obesity, intellectual disability, and resistance to several hormones are still extensively related to AHO, they may not be directly associated with genetic defects in GNAS." (PMID 29499646, 2018).
pancreatic cancer (33 papers, 2003 to 2025). "Targeting oncogenic mutations like KRAS and GNAS offers a potential avenue for preventing pancreatic cancer development, but ongoing clinical trials are necessary to determine prophylactic efficiency." (PMID 40074443, 2025). "GNAS is frequently associated with several malignancies, such as bone marrow and pancreatic cancers, making these predictions crucial for further investigation." (PMID 39684787, 2024). "Primers were designed for hotspot regions in the KRAS (codon 12 and 13) and GNAS (codon 201) genes to detect well-characterized driver mutations in pancreatic cancer by Sanger sequencing." (PMID 38472986, 2024). "GNAS (guanine nucleotide binding protein, alpha stimulating) mutations are observed in bone marrow and pancreatic cancers." (PMID 39684787, 2024). "AC hyperactivation also contributes to tumorigenesis in the context of oncogenic GNAS mutations although the roles of cAMP-dependent signaling in pancreatic cancer are poorly understood." (PMID 33652890, 2021). "Oncogenic mutations and amplifications of the GPCR-associated Gα stimulatory subunit (GNAS), which constitutively increase AC activity, are frequent in pancreatic cancer (2–11%)." (PMID 33652890, 2021). "Pancreatic IPMNs specifically have GNAS mutation at exon 8 (Arg201Cys or Arg201His) among pancreatic neoplasms." (PMID 34674710, 2021). "In pancreatic tumors, for example, GNAS SWI arginine and p.V633M mutations in the downstream adenylate cyclase ADCY8 are mutually exclusive in addition to those affecting DRY Arginine of upstream GPCRs." (PMID 31337866, 2019). "The R201H mutation of GNAS is highly specific for IPMN among pancreatic tumors, and the most characteristic feature of IPMN is excessive production of mucin." (PMID 24498386, 2014). "HPDE was expected to show the “pure” phenotype of mutated GNAS, whereas the pancreatic cancer cells were expected to manifest the phenotype of mutated GNAS plus mutated KRAS (the latter corresponds to common mutations found in IPMN)." (PMID 24498386, 2014). "GNAS is mutated in approximately 60% of IPMNs and in some invasive pancreatic cancers arising in association with an IPMN." (PMID 23197977, 2012). "Other studies reported the role of GNAS mutations in the progression towards pancreatic cancer." (PMID 34884643, 2021). "However, recent studies have shown that a pancreatic cancer lesion—intraductal papillary mucinous neoplasm (IPMN)—bears GNAS mutation." (PMID 29104223, 2017). "For instance, previous studies have shown that GNAS mutations can provide a help in the risk stratification and surveillance of patients with pancreatic cancer, which may inform the diagnosis and management of PAAD." (PMID 29212244, 2017). "Hence, mutated GNAS is considered a key molecule that distinguishes IPMN from other pancreatic tumors." (PMID 24498386, 2014). "GNAS, a gene encoding G protein stimulating α subunit, is frequently mutated in intraductal papillary mucinous neoplasms (IPMNs), which are indolent and slow-growing pancreatic tumors that secrete abundant mucin." (PMID 24498386, 2014). "Next, we queried four databases through the cBioPortal platform (MSK-IMPACT, CTPAC, TCGA, ICGC) and reviewed GNAS and KRAS mutation data of 2759 pancreatic cancer patients." (PMID 40002298, 2025). "IPMN with associated invasive carcinoma and pancreatic cancer have an overlapping yet distinct genetic mutation, such as KRAS and GNAS." (PMID 34178672, 2021). "Many studies showed that IPMN and pancreatic cancer have the same somatic mutations, such as in KRAS and GNAS." (PMID 31338331, 2019).
pancreatic cancer (continued). "Both MAP2K4 and GNAS are known to be involved in pancreatic cancer [Cancer Gene Census and Intogen databases]." (PMID 28473845, 2017). "Alterations to PRKACB function through gene fusion are mutually exclusive from GNAS mutation in biliary tract cancer and either mutually exclusive in pancreatic cancer or not completely mutually exclusive." (PMID 39342354, 2024). "Although functional studies of GNAS mutations in IMA have not been reported, codon 201 GNAS mutants function as oncogenes in KRAS-driven GEMMs of pancreatic cancer, which expresses some of the same foregut markers as IMA." (PMID 33821796, 2021). "Further studies of the potential dual role of MAP2K4 and GNAS might help elucidating the molecular basis for the complex bidirectional relationship observed between diabetes and pancreatic cancer." (PMID 28473845, 2017). "To characterize phenotypic changes caused by the mutated GNAS in pancreatic ductal cells, we employed HPDE cells (an immortalized cell line derived from healthy pancreatic duct epithelial cells) and pancreatic cancer cell lines (PK-8, PCI-35, and MIA PaCa-2) carrying KRAS mutations." (PMID 24498386, 2014). "As we observed KRAS mutations to closely associate with wild-type GNAS IPMN lesions, we decided to use a broader cohort of PDAC cases, not uniquely limited to IPMN, to test whether this association is relevant in a more general context in pancreatic cancer." (PMID 40002298, 2025). "Sporadic activating variants in the GNAS locus not only result in replacement of normal bone with fibro-osseous tissue in CFD lesions, but also is mutationally activated in various cancer types, such as growth hormone-secreting pituitary tumors, pancreatic cancer and colorectal cancer." (PMID 38287340, 2024). "PK-8, PCI-35, and MIA PaCa2 are pancreatic cancer cell lines harboring the following gain-of-function mutations of KRAS: G12R in PK-8 cells, G12D in PCI-35 cells, and G12C in MIA PaCa-2 cells, but no mutations in the mutational hotspots of exons 8 and 9 (including codons 201 and 227) of GNAS." (PMID 24498386, 2014). "GNAS mutant patients were more likely to present with a resectable disease rather than locally advanced or metastatic pancreatic cancer (OR 1.8, 95% CI 1.1–2.8, p < 0.05)." (PMID 40002298, 2025). "Since the gene panel did not include GNAS, VHL, or RNF43, we could not rule out the possibility of IPMN-derived pancreatic cancer associated with these genes." (PMID 36980386, 2023).
pseudopseudohypoparathyroidism (31 papers, 2011 to 2025). A disease characterized by a constellation of clinical features collectively termed Albright hereditary osteodystrophy (AHO) but no evidence of resistance to parathyroid hormone (PTH), which is seen in other forms of pseudohypoparathyroidism (PHP). "Genetic defects affecting GNAS can cause several human diseases such as Pseudopseudo hypoparathyroidism (PHP, MIM:612462, 603233, 103580 ), end-organ resistance to parathyroid hormone (PTH, MIM: 612463), progressive osseous heteroplasia (POH, MIM: 166350)." (PMID 39285472, 2024). "In contrast, pseudopseudohypoparathyroidism (PPH) results from paternal GNAS pathogenic variants." (PMID 40125101, 2025). "An inactivating mutation in the GNAS gene causes either pseudohypoparathyroidism 1a (PHP1A) when it is maternally inherited or pseudopseudohypoparathyroidism (PPHP) when it is paternally inherited." (PMID 24651309, 2014). "Due to this imprinting phenomenon, paternally inherited loss of function GNAS variants do not result in hormone resistance and the resulting phenotype is called pseudopseudohypoparathyroidism (PPHP)." (PMID 40806967, 2025). "AHO without any evidence of hormonal resistance, called pseudopseudohypoparathyroidism, is due to paternal loss-of-function mutations in GNAS." (PMID 28515031, 2017). "On the other hand, paternal transmission of the mutated GNAS allele is not accompanied by hormone resistance, and is then classified as pseudopseudohypoparathyroidism (PPHP)." (PMID 32647264, 2020). "AHO without biochemical abnormalities is known as pseudopseudohypoparathyroidism (PPHP) and is due to mutation of GNAS on the paternal allele of chromosome 20q13 (OMIM#612463)." (PMID 29971010, 2018).
breast carcinoma (29 papers, 2013 to 2025). "GNAS overexpression is associated with increased migration and proliferation in breast cancer models, while GNAS knockdown is able to inhibit EMT and breast tumour growth in vivo." (PMID 38097740, 2024). "Taken together, activation of GNAS by the oncogenic R201C mutation led to immune evasion in mouse models of liver and breast cancers." (PMID 37714844, 2023). "In addition, upregulated CCND2, SNHG16, MYC, and GNAS levels were associated with accelerating cell cycle progression, as well as promoting growth and metastasis in lung cancer, breast cancer, and colon cancer." (PMID 37007962, 2023). "It has been reported that the amplification of GNAS may contribute to the pathogenesis of breast cancer and is associated with the survival of patients with invasive breast carcinoma." (PMID 31036036, 2019). "SALL4 and GNAS were known to promote breast cancer progression, and previously reported to be involved with SE hijacking events." (PMID 39322849, 2024). "In this study, we found a higher PSI value in breast cancer patients than in normal samples for COMMD4_AS2, GNAS, MATR3, RHOC and COMMD4_AS1, whereas the PSI value was lower for MARK3, POLDIP3 and FASTK." (PMID 36725888, 2023). "GNAS was found to induce breast cancer cell proliferation and metastasis through the PI3K/AKT/Snail1/E-cadherin signaling pathway." (PMID 37202799, 2023). "Studies on GNAS protein expression demonstrated that the high expression of the GNAS protein enhanced breast cancer cell proliferation and migration, as well as HCC cell growth and invasion." (PMID 35052777, 2022). "Previous studies have shown that DNA methylation levels of imprinted domains of GNAS in primary breast cancer, lung cancer, and ovarian cancer are very different from those in normal tissues." (PMID 35115040, 2022). "GNAS is observed in both tumor and normal samples, as well as in the hemimethylation study for breast cancer cell lines." (PMID 33711952, 2021). "Other well-known breast cancer associated genes that were highly expressed in both cell systems included GATA3, GNAS, FASN and NCOA3." (PMID 34680485, 2021). "Reportedly, the methods developed in this study were successful in determining the spatial variation in the expression of 102 genes, including several breast cancer biomarkers such as GNAS, FASN, and DDX5." (PMID 34441338, 2021). "We next tested whether GNAS activation could promote immune evasion of 4T1-derived breast cancer in mice." (PMID 37714844, 2023). "Although we found variabilities along the stages, which reflects the heterogeneity of this disease, COMMD4_AS2, MARK3, MATR3, POLDIP3, COMMD4_AS1, and GNAS underwent AS switches in almost all stages of breast cancer, while RHOC displayed significant AS switches during stage IIB." (PMID 36725888, 2023). "It has been shown that GNAS promotes breast cancer cell proliferation and epithelial–mesenchymal transformation (EMT) through the PI3K/Akt/Snail1/E-cadherin signaling pathway, which may be responsible for the malignant progression and metastasis." (PMID 35115040, 2022). "Prior studies link FASN, GNAS, and IGHA1 to breast cancer progression and suggest prognostic potential." (PMID 41263940, 2025). "Clinically relevant amplification drivers such as ERBB2 in breast cancers (FF: 7.7%, FFPE:4.7%), GNAS (20q13) in colorectal cancers (FF: 6.4%, FFPE: 4.5%), and CCND1 (FF: 6.9%, FFPE: 8.5%) were comparably retrieved." (PMID 39231944, 2024). "We found that METTL3 depletion promoted exon inclusion of the alternative exons of GNAS, MATR3, POLDIP3 and promoted skipping of the alternative exons of COMMD4, MARK3 and the non-m6A modified transcripts FASTK and EXOC7 in both breast cancer cell lines." (PMID 36725888, 2023). "Hotspots were also identified at GNAS, RUNX1, and MDM2, all recognised as breast cancer genes, even if less frequent." (PMID 30252041, 2018).
breast carcinoma (continued). "These included genes such as SCUBE3, MARCKSL1 and PGK1 in lung cancer, SOX4 and GNAS in breast cancer and hepatocellular carcinoma, HEG1 in hepatocellular carcinoma, PLS3 in pancreatic adenocarcinoma, FBN1 and SPARC in gastric cancer and CST1 in gastric cancer and breast cancer." (PMID 40430098, 2025). "We observed that the AS events for COMMD4_AS2, GNAS, MATR3,COMMD4_AS1 and RHOC displayed a significant higher PSI value in cancer patients than in normal samples, while the PSI values were significantly lower for MARK3, POLDIP3 and FASTK in patients with breast cancer." (PMID 36725888, 2023). "This analysis identified 30/229 known cancer genes (T200 targeted platform) and 11/40 TCGA breast cancer genes that were differentially expressed relative to the normal breast cells, including KRAS, GATA3, CCND1, CDH1, GNAS, and several others." (PMID 28794488, 2017). "Although AC083799.1, C10orf55, and GNas.AS1 have not been reported in glioma, some studies have found that they play important roles in the occurrence and development of other tumors, such as breast cancer, colon cancer, acute myeloid leukemia, and endometrial cancer." (PMID 36033510, 2022).